ZNF281 (zinc finger protein 281)
Diseases named in the same sentence as ZNF281 in open-access papers (continued):
Sharing a sentence is not in itself a finding about the gene and the disease.
cancer (continued). "For instance, ZNF830 promotes homologous-recombination repair and mediates cancer chemoresistance; ZNF281 acts as a potential diagnostic marker for oral squamous cell carcinoma; and ZNF419 might serve as a potential prognostic and immunological pan-cancer biomarker." (PMID 40599863, 2025). "ZNF143 and ZNF281 may serve as novel targets for future cancer therapeutics." (PMID 39281319, 2024). "Whether ZNF281 participates in other biological processes in cancer remains elusive." (PMID 37880213, 2023). "Furthermore, for a more complex and systematic understanding of ZNF281 in tumors, the expression level of ZNF281 was also investigated in pan-cancer and an upregulated phenomenon in most tumors compared to their related normal tissues and adjacent tissues was observed." (PMID 36685971, 2022). "In conclusion, our data focused on the dual role of ZNF281 and showed that it was a potential biomarker for regeneration and might also be functional in the diagnosis and clinical prediction of multiple types of cancer." (PMID 36685971, 2022). "Moreover, reduced survival expectations were observed in high ZNF281 cancer." (PMID 36685971, 2022). "Moreover, the ZNF281 expression level was related to worse prognosis in 10 types of cancer." (PMID 36685971, 2022). "The key to understanding ZNF-281’s role in cancer progression is to acknowledge that its expression is regulated by various cancer type-related miRNAs, phosphorylation and acetylation depending on the cell’s environment and protein co-factors, and its function may vary in different types of cancer." (PMID 34071380, 2021). "Additional experiments will be needed to answer all of these questions, which will significantly contribute to the understanding of the control of ZNF281 stability in cancer cells and may provide opportunities for developing innovative anticancer therapeutic modalities." (PMID 29179460, 2017). "In addition, DNA damage-inducing drugs can increase ZNF281 expression in cancer cell lines." (PMID 29179460, 2017). "In addition, therapeutic approaches aimed at disrupting key regulatory interactions, including those involving TAF1, MYC, MAZ, and other TFs such as KLF15 and ZNF281, may suppress tumor growth and modulate stress adaptation, thereby enabling more precise interventions against cancer." (PMID 41155227, 2025). "ZNF281, which is an epithelial–mesenchymal transition (EMT)-inducing transcription factor, is also upregulated in various malignant tumors." (PMID 39281319, 2024). "They found that ZNF281 up-regulated the phosphatase and tensin homolog (PTEN) by down-regulating Mir-221 in NSCLC, thus constraining cancer cell propagation and death." (PMID 36817434, 2023). "Other ZNF members including ZNF281, ZNF185 and ZNF750 serve as oncogenes or tumor suppressor genes in different cancers." (PMID 34670480, 2021). "ZNF281 is an EMT-inducing transcription factor (EMT-TF) involved in the regulation of pluripotency, stemness, and cancer." (PMID 30619271, 2018). "Recently, ZNF281 has been characterized as an EMT-inducing transcription factor (EMT-TF), suggesting its involvement in the regulation of pluripotency, stemness, and cancer." (PMID 30619271, 2018). "ZNF281 has been characterized as an epithelial-to-mesenchymal transition (EMT)-inducing transcription factor, suggesting its involvement in the regulation of pluripotency, stemness, and cancer." (PMID 36142169, 2022). "ZNF281 is a zinc-finger transcriptional regulator that has been characterized as an epithelial-to-mesenchymal transition (EMT)-inducing transcription factor, suggesting its involvement in the regulation of pluripotency, stemness, and cancer." (PMID 36142169, 2022). "Thus, our results define a late ZNF281-dependent regulatory step of NHEJ complex assembly at DNA lesions and suggest additional possibilities for cancer patients’ stratification and for the development of personalised therapeutic strategies." (PMID 31570788, 2020).
tumor (20 papers, 2017 to 2025). "In patients with LARC who were treated with neoadjuvant radiotherapy (NART), higher ZNF281 expression in malignant tissue was associated with a poorer prognosis and lesser degree of tumor regression." (PMID 37939252, 2023). "Considering that SMAD7 acts as a transcriptional regulator and ZNF281 is a tumor-suppressive long non-coding (lnc)RNA, an increase in hsa-miR-33a-5p could lead to the downregulation of these factors and consequently to a loss of tumor suppression capability." (PMID 36979715, 2023). "H&E staining showed a significantly higher number of tumor lesions in the lung of mice injected with HeLa-ZNF281 cells compared with control." (PMID 39518154, 2024). "The zinc finger transcription factor 281 (ZNF281)/ZBP-99 protein specifically binds to GC-rich DNA sequences and regulates gene expression, and it has been shown to promote tumor progression." (PMID 39518154, 2024). "We assessed the relationship between ZNF281 and the tumour microenvironment (TME) and combined bulk-RNA and single-cell RNA data to analyse the relationship between ZNF281 and immune infiltration." (PMID 38880820, 2024). "In patients who had LARC and were being treated with NART, there was a correlation between a greater level of ZNF281 expression and a weaker tumour shrinkage and a worse prognosis." (PMID 37939252, 2023). "Taken together, our findings provide new insights into the dual role of ZNF281, and we found that it was a potential biomarker for regeneration and tumor prognosis." (PMID 36685971, 2022). "In NSCLC, overexpression of the ZNF-281 gene, resulting in promotion of cell apoptosis and inhibition of cell proliferation, exhibits tumor-suppressive properties." (PMID 34071380, 2021). "Based on this and our previous experimental evidence, we explored the possibility of using ZNF281 expression levels as a predictive marker of resistance to the DNA-damaging agents commonly used as anti-tumour therapies (radio- and chemo-therapies)." (PMID 31570788, 2020). "It was observed that mice from the HCT116 cells transfected with β-TrCP2 and ZNF281 showed significantly decelerated tumor growth." (PMID 29179460, 2017). "Furthermore, in primary CRC samples, expression of ZNF281 increased during tumor progression and correlated with recurrence." (PMID 41155227, 2025). "ZNF281 modulates the Wnt/β-catenin pathway to influence malignant tumor behavior." (PMID 38880820, 2024). "Moreover, nude mice injected with ZNF281-overexpressing cell lines developed more tumor lesions in the lungs compared to those injected with control cell lines." (PMID 39518154, 2024). "Notably, a previous contradictory study showed that ZNF281 was recruited to DNA breaks to facilitate DNA repair in tumour cells." (PMID 36514923, 2023). "Thus, we analyzed the relationship between ZNF281 expression and tumor regression grade (TRG) in pretreatment biopsies of 126 patients who did receive NART after surgery." (PMID 37939252, 2023). "Zinc finger protein 281 (ZNF281) has been shown to promote tumor progression." (PMID 37880213, 2023). "We found that ZNF281 is expressed at variable levels in both tumor types." (PMID 31782884, 2020). "Conversely, a high expression of ZNF281 could favour the survival of tumour cells subjected to genotoxic therapies, thus triggering a process of chemoresistance and tumour regrowth." (PMID 31570788, 2020). "It is, indeed, tempting to speculate that ineffective DNA-damaging treatments could be implemented with PARP inhibitors in order to sensitise ZNF281 highly expressing tumours that show resistance to genotoxic therapies alone." (PMID 31570788, 2020).
tumor (continued). "In addition, ZNF281 induces epithelial-mesenchymal transition (EMT) in tumour cells and controls the expression of several key EMT-associated genes." (PMID 31570788, 2020). "Interestingly, ZNF281 expression was upregulated in patient tumour samples, confirming an important role of ZNF281 in CRC." (PMID 29152378, 2017). "The aberrant expression of zinc finger protein 281 (ZNF281) and the over-activation of the Wnt/β-catenin pathway are oncogenic factors and confer tumor chemoresistance." (PMID 38880820, 2024). "In summary, this study clarified the important roles and molecular mechanisms of ZNF281 in regulating mitochondrial biogenesis in HCC, which facilitates tumor invasion and metastasis." (PMID 37880213, 2023). "By Cox regression, univariate Cox regression analysis revealed that ZNF281 expression level, T stage after pCRT, N stage after pCRT, TNM stage and Tumor downstage after pCRT correlated with OS." (PMID 37939252, 2023). "Next, according to the mechanistic studies, circ‐0008003 functioned as a ceRNA of ZNF281 in NSCLC by acting as the endogenous sponge for miR‐488, which was proved to be a tumour suppressor in NSCLC." (PMID 33320427, 2022). "It was validated in this research that circ‐0008003 triggered tumour formation in NSCLC, which was adjusted via miR‐488/ZNF281 axis, casting a novel light on the resultful target for treating NSCLC and predicting the prognosis." (PMID 33320427, 2022). "In recent years, several experimental studies revealed a role of ZNF281 (C2H2-type) in tumorigenesis and tumour invasion." (PMID 29152378, 2017). "Zinc finger protein 281 (ZNF281) is a focus of research and a potential target for tumours." (PMID 38880820, 2024). "To test this hypothesis, we firstly investigated the expression patterns of β-TrCP2 and ZNF281 in human 60 CRC tissues and corresponding adjacent non-tumor tissues." (PMID 29179460, 2017). "ZNF281 overexpression did not influence HeLa cell proliferation or tumor size in situ." (PMID 39518154, 2024). "PGC-1α functions as tumor suppressor in HCC, Our results showed direct repression of ZNF281 on PGC-1α, which partly explained the down-regulation of PGC-1α in HCC, and also suggested that silencing of PGC-1α might be an important mechanism for ZNF281 to promote invasion and metastasis of HCC." (PMID 37880213, 2023). "Furthermore, ZNF281 in CAFs upregulated CCL2 and CCL5 rather than VEGFA expression, which stimulated angiogenesis and vascular permeability through P38 MAPK signaling in endothelial cells, consequently contributing to lung PMN formation in tumor metastasis." (PMID 36438499, 2022).
ZNF281 also shares sentences with these, for which no sentence is quoted: fibrosis (3 papers); lung adenocarcinoma (2); lung carcinoma (2); rhabdomyosarcoma (2); Stomach adenocarcinoma (2); alcohol abuse (1); arterial hypertension (1); Breast invasive carcinoma (1); cervical squamous cell carcinoma (1); cholangiocarcinoma (1); diabetes mellitus (1); endocervical adenocarcinoma (1); endometrial carcinoma (1); Esophageal carcinoma (1); head and neck squamous cell carcinoma (1); Infertility (1); liposarcoma (1); lymphoma (1); melanoma (1); myocardial infarction (1); oral cancer (1); Pan (1); round cell liposarcoma (1); serous borderline ovarian tumors (1).